JAK2 (Janus kinase 2)
Diseases named in the same sentence as JAK2 in open-access papers (continued):
Sharing a sentence is not in itself a finding about the gene and the disease.
thyroid nodule (1 paper, 2024). A small circumscribed mass in the THYROID GLAND that can be of neoplastic growth or non-neoplastic abnormality. "Transcriptomics suggested that the (IL-6, TNF-α, IL-1β)/JAK2/STAT3/VEGF pathway may be one of the key mechanisms in the treatment of thyroid nodules by JJJG." (PMID 39494342, 2024). "Meanwhile, this study is the first to explore and suggest that the (IL-6, TNF-α, IL-1β)/JAK2/STAT3/VEGF signaling pathway may be involved in regulating the development of thyroid nodules and is one of the possible therapeutic targets for JJJG." (PMID 39494342, 2024). "Key genes involved in thyroid nodules pathogenesis and JJJG treatment were revealed, such as Il6, Il1b, Jak2, Stat3 and Vegfa, etc.." (PMID 39494342, 2024). "This study indicates that JJJG efficiently ameliorates thyroid nodules by regulating the levels of FT3, FT4 and TSH in serum and suppressing (IL-6, TNF-α, IL-1β)/JAK2/STAT3/VEGF pathway in thyroid tissue, providing a potential therapeutic approach for thyroid nodules." (PMID 39494342, 2024). "Therefore, through transcriptomics in conjunction with literatures, we speculated that JJJG may treat thyroid nodules via (IL-6, TNF-α, IL-1β)/JAK2/STAT3/VEGF pathway." (PMID 39494342, 2024).
toxic epidermal necrolysis (1 paper, 2025). Toxic epidermal necrolysis (TEN) is an acute and severe skin disease with clinical and histological features characterized by the destruction and detachment of the skin epithelium and mucous membranes. "The results showed a substantial association between apalutamide and Stephen Johnson Syndrome/toxic epidermal necrolysis, and the mechanism behind this association may be the binding of apalutamide to JAK1 and JAK2." (PMID 40017595, 2025).
uterine cancer (1 paper, 2017). Primary or metastatic malignant neoplasm involving the uterine corpus and/or the cervix. "Unorthodoxically, this study in NSCLC and the previous studies of JAK1 in uterine cancer also suggest that JAK1 and JAK2 have tumor suppressor function, deficiencies of them could allow tumor cells to escape T-cell mediated immune surveillance." (PMID 28977839, 2017).
Vertigo (1 paper, 2022). An abnormal sensation of spinning while the body is actually stationary. "Taken together, the data acquired in the present study elucidated the mechanism by which circ_0000811 overexpression ameliorated CI-induced vertigo through attenuating the apoptosis of neurons via the modulation of the miR-15b/Prkar2a/JAK2/STAT1 cascade." (PMID 35508616, 2022). "To substantiate the circ_0000811/miR-15b/Prkar2a/JAK2/STAT1 regulatory axis in vivo, we performed a series of gain- and loss- of functions assays on mice with experimental CI-induced vertigo." (PMID 35508616, 2022). "The results unraveled that the AG490-induced inhibition of the JAK2/STAT1 signaling pathway alleviated CI-induced vertigo through repression of neuronal apoptosis, its combination with circ_0000811 strengthening the effects of circ_0000811 overexpression alone." (PMID 35508616, 2022). "Hence, circ_0000811 may mitigate CI-induced vertigo through suppressing the JAK2/STAT1 signaling pathway to attenuate neuronal apoptosis." (PMID 35508616, 2022). "Circ_0000811 sponged miR-15b to inhibit its expression and augment Prkar2a expression, whereby the JAK2/STAT1 signaling pathway was repressed, and the apoptosis of neurons was thus attenuated to mitigate the CI-induced vertigo." (PMID 35508616, 2022). "First, we observed that the phosphorylation levels of JAK2 and STAT1 were increased in the MVN of mice with CI-induced vertigo as well as in OGD-exposed cells." (PMID 35508616, 2022). "Furthermore, our data revealed that Prkar2a inactivated the JAK2/STAT1 signaling pathway, thus attenuating neuronal apoptosis in CI-related vertigo." (PMID 35508616, 2022). "Furthermore, inactivation of the JAK2/STAT1 signaling pathway exerted an anti-apoptotic effect in OGD-induced neurons and an alleviatory effect in mice with CI-induced vertigo with Prkar2a overexpression and circ_0000811 overexpression." (PMID 35508616, 2022).
vitamin D deficiency (1 paper, 2020). A nutritional condition produced by a deficiency of VITAMIN D in the diet, insufficient production of vitamin D in the skin, inadequate absorption of vitamin D from the diet, or abnormal conversion of vitamin D to its bioactive metabolites. "There was a significant relationship between JAK2 V617F mutation positivity and vitamin D deficiency in PV patients (P = 0.024)." (PMID 32158346, 2020). "Further comprehensive studies are required to elucidate the relationship between vitamin D deficiency and the JAK2 V617F mutation in this patient population." (PMID 32158346, 2020). "Although vitamin D deficiency was more common in both groups with the JAK2 V617F mutation, more comprehensive studies on the relationship between JAK2 V617F mutation positivity and vitamin D should be conducted." (PMID 32158346, 2020). "There was a remarkably higher prevalence of vitamin D deficiency in JAK2 mutation-positive ET and PV patients." (PMID 32158346, 2020). "In our study, vitamin D deficiency was more frequent in JAK2 V617F-positive PV and ET patients." (PMID 32158346, 2020). "There was a significant relationship between JAK2 positivity and vitamin D deficiency." (PMID 32158346, 2020).
tumor (1,108 papers, 2002 to 2026). "In two instances, resistance-associated mutations in B2M or JAK2 were detected as subclonal events in the pre-treatment tumor and clonal in the resistant tumor." (PMID 39933900, 2025). "For the single slide Perturb-map dataset, the perturbation (Jak2-KO, Tgfbr2-KO, Ifgbr2-KO, or control) and spot type (tumor, normal, or periphery) are encoded in the perturbation module." (PMID 41292874, 2025). "The Jak2/Stat3 pathway served as a key mediator of oncogenesis and tumor angiogenesis, and its dysregulation was linked to poor prognosis in multiple cancer types." (PMID 40840329, 2025). "Jak2/Stat3 in tumor-associated macrophages/myeloid cells is also crucial for inducing cancer-promoting inflammatory immune responses while inhibiting antitumor immune responses." (PMID 40801626, 2025). "In parallel, JAK1 and JAK2 hyperactivation is commonly linked to cytokine-driven signaling that sustains tumor growth, while TYK2 shows dual behavior: supporting immune surveillance in some contexts but fostering immune evasion in others." (PMID 41438753, 2025). "Our data demonstrate ITGA2hi‐PTC cell‐driven polarization of tumor‐associated macrophages (TAMs) toward immunosuppressive M2 phenotypes via JAK2/STAT3 activation." (PMID 40985182, 2025). "Studies have indicated that the α7 nAChR present in tumor-associated macrophages has the ability to inhibit tumor metastasis via the JAK2/STAT3 signaling pathway." (PMID 38808717, 2025). "Analysis of tumor-associated RNA revealed high JAK2, PD-L1, CCL2, and CXCL10 expression in ALKBH5-overexpressing mice compared to wild-type mice." (PMID 38872221, 2024). "As well delineated in JAK2‐mutated cases, chronic inflammation contributes to tumor clonal expansion by promoting the selective growth of tumor cells." (PMID 39320136, 2024). "After adjustment for tumor type, the JAK2 mutation status remained an independent prognostic factor related to OS." (PMID 38200372, 2024). "In comparison, it is more plausible to target the upregulated FXR in NSCLC that specifically induces the excessive or pathogenic IL-6/Jak2/STAT3 signaling pathway on the matter of tumor metastasis." (PMID 38360812, 2024). "Among them, VEGF-A amplification is associated with neo-angiogenesis, and JAK2 and PD-L1/PD-L2 amplification leads to formation of the immunosuppressive tumor microenvironment." (PMID 38733489, 2024). "Previous studies have documented that the Jak2/STAT3 signaling pathway is associated with tumor metastasis and angiogenesis." (PMID 38360812, 2024). "Due to its ability to bind multiple receptors, CCL5 has been linked to multiple pathways that mediate tumor progression, including the JAK2/STAT3, NF-κB, TGFβ, PI3K/Akt, HIF-α, and Ras-ERK-MEK pathways." (PMID 39409924, 2024). "Tumor-associated macrophages (TAMs) can induce EMT by regulating the JAK2/STAT3/miR-506-3p/FoxQ1 axis to enhance CRC migration and invasion." (PMID 38213716, 2024). "ALKBH5 and tumor-associated macrophage-secreted IL-6 showed a synergistic effect to activate the JAK2/p-STAT3 pathway in cancer cells." (PMID 38872221, 2024). "Univariable Cox regression analyses of PFS for age, gender, cancer type, drug type, and JAK2 mutation status revealed that the JAK2 mutation status and tumor type were prognostic factors." (PMID 38200372, 2024). "In each patient, and in agreement with the original report, we discovered a cluster(s) corresponding to the neoplasm along with the corresponding driving mutations in JAK2, DNMT3A and TET2 genes." (PMID 37026484, 2023). "SOCS1 and SOCS3 were important negative regulators of tumor-associated immune cells during tumor development, PE inhibited the activation of JAK2 in SOCS1." (PMID 37355637, 2023). "Whole exome analysis of the resistant tumor clones identified loss-of-function mutations in the genes encoding interferon-receptor-associated Janus kinase 1 (JAK1) or Janus kinase 2 (JAK2), which leads to insensitivity to INFα, β and γ." (PMID 36674809, 2023).
tumor (continued). "We further checked the gene expression in primary tumor versus normal tissue for genes JAK2, PRDM16, LRP1B, NIN, and NKX2-1 with variants repeatedly enriched in variant-based analysis, and, FANCE, enriched in gene-based burden testing, using the TCGA database." (PMID 35954343, 2022). "CD163+ tumor-associated macrophages can secrete IL-6 to activate tumor cells JAK2/STAT3, promoting EMT and CTC-mediated metastasis, which is closely related to poor prognosis of patients." (PMID 36568117, 2022). "Recent studies suggest that extracellular HSP90α induces MyD88-IRAK complex-associated IKKα/β-NF-κB/IRF3 and JAK2/TYK2-STAT-3 signaling pathways in macrophages to promote tumor M2 polarization." (PMID 36158677, 2022). "Here the authors show that a RNA binding protein, DENR, positively regulates the translation of JAK2 and induces PD-L1 expression in tumor cells, associated with immune evasion." (PMID 35440133, 2022). "The JAK2/STAT3 signaling pathway is associated with a malignant progression of tumor cells, such as cell proliferation, invasion, and immunoregulation." (PMID 33788424, 2021). "It is also possible that these cells are functionally suppressed in the tumor microenvironment (e.g., mutations in JAK1 and JAK2 genes in tumor cells can lead to inappropriate antigen presentation)." (PMID 34502043, 2021). "In other words, the cell-based assays that have been utilized to test the efficacy/potency of Jak2 inhibitors are cell/tumor models expressing mutated Jak2V617F." (PMID 34680353, 2021). "Recent research shows that regulatory mechanisms of CTC-mediated tumor metastasis involve Tumor-Associated Macrophages (TAMs) by regulating the JAK2/STAT3/miR-506-3p/FoxQ1 axis." (PMID 32429087, 2020). "For instance, if some tumor cells have JAK2 V617F, and other from the same patient bear JAK2 V617F with an additional somatic mutation, then this indicates that JAK2 V617F came first." (PMID 33255170, 2020). "Further studies showedthat PAR-1 activation-mediated tumor cell apoptosis is associated with tyrosinephosphorylation of JAK2 and STAT1, and translocation of STAT1 to the nucleus." (PMID 30785507, 2019). "Suppressor of cytokine signaling 1 (SOCS1) is a postulated tumor suppressor gene associated with growth arrest of tumor cells, rapid dephosphorylation of JAK2, and silencing of cyclin D1." (PMID 30884772, 2019). "Treatment of ALK− ALCL tumor bearing mice carrying JAK1 and STAT3 mutations with ruxolitinib, a JAK1/JAK2 inhibitor, led to inhibition of tumor formation, which demonstrates the therapeutic potential of targeting the JAK1/STAT3 pathway." (PMID 31684088, 2019). "Curcumin has been found to exert its anti‐inflammatory and anti‐carcinogenic effects by targeting JAK2 signalling in different type of neoplasms and injuries, but the effects of this phytochemical on JAK2‐mutated cells have been poorly studied until now." (PMID 31033209, 2019). "We then analyzed microRNA (miRNA) transcriptional targets of STAT327, and observed increased miR-21 and miR-181b in tumor samples carrying mutations in PTPRT or JAK2, while non STAT3 targets, such as miR-126, were similar." (PMID 31844068, 2019). "A second patient with the same tumour demonstrated a JAK2 mutation, a kinase with important roles in cell growth and development." (PMID 29541442, 2018). "During this tumor's evolution, four different JAK2 inactivating mutations occurred, all on subclonal branches of the phylogenetic tree, with several of the lesions apparently having compound heterozygous inactivation of the gene." (PMID 28810143, 2017). "LOH for JAK1 was detected in 25% (15 of 59) and for JAK2 in 76% (45 of 59) of the cell lines suggesting a high risk of resistance development in the course of an effective anti-tumour T-cell response." (PMID 28561041, 2017). "All of these alterations in addition to gene mutations would predispose to JAK1/JAK2 inactivation and IFNγ-resistance in tumours if put under selective pressure by the immune system." (PMID 28561041, 2017).
tumor (continued). "A previous study demonstrated that JAK2/STAT3 was also associated with the development of tumor cachexia by inducing a systemic inflammatory response." (PMID 28489606, 2017). "Collectively, we show that ROS-mediated oxidative damage is prevented in steatotic JAK2 deficient livers, which correlates with delayed tumour onset in the GHtg background." (PMID 27713471, 2016). "In contrast, JAK2 deficiency delays tumour formation in GHtg mice, which is linked to insignificant oncogenic STAT3 signalling and reduced ROS-induced oxidative damage." (PMID 27713471, 2016). "They engineered an associated mutation in Janus kinase 2 (JAK2) in HSCs and detected damage of the bone marrow niche through Nestin+ MSCs reduction, which further drive HSCs into neoplasia." (PMID 26236348, 2015). "The anti-tumour action of LDFI was associated with the inhibition of several leptin-induced pathways such as JAK2, STAT3, AKT and MAPK and a reduction in Cyclin D1 expression." (PMID 25721149, 2015). "In order to confirm the experimental system to be reproducible, we focused on JAK2, as it has been reported to have association with tumor genesis in previous studies." (PMID 26202837, 2015). "Collectively, these data suggest that anti-tumor activity and pro-apoptotic effect of icaritin on human U266 cells is associated with the mechanism involved in targeting IL-6/JAK2/STAT3 signaling pathway." (PMID 25865044, 2015). "While mutations affecting JAK2 (JAK2mu) have been widely investigated in recent years, the rarer yet more structurally and clinically varied JAK2 translocation neoplasms remain weakly characterized." (PMID 23372669, 2013). "The antitumor activity of SOID-8 is associated with inhibition of JAK2/STAT3 signaling in these tumor cells." (PMID 23166634, 2012). "JAK2 mutations, such as the common V617F substitution and the less common exon 12 mutations, are frequently detected in such tumor cells and have been incorporated into the diagnostic criteria published by the World Health Organization since 2008." (PMID 21789226, 2011). "The causal relationship between constitutive JAK2 activity and neoplasia has resulted in the development of a variety of potent and selective JAK2 small molecule inhibitors." (PMID 21533169, 2011). "Both cytoplasmic and membrane-associated JAK2 expression was significantly different between the normal ovaries and the tumour groups." (PMID 19088723, 2009). "Research shows that subjects with JAK2 mutations present an increased proportion of circulating MDSCs, which correlates with disease progression, substantial immunosuppressive mechanisms, and distinctive tumor-promoting and metastatic attributes." (PMID 41268532, 2025). "In addition, a heterogeneous, but increased expression of IFN-γ signaling components was found in BMB of JAK2-mutated samples with the highest expression in lymphocytes and monocytes, accompanied by increased tumor infiltrating lymphocytes (TIL)." (PMID 40764668, 2025). "Furthermore, deficiency of circRNA-14,052 reduced xenograft tumor growth in vivo through targeting miR-214-3p/IKBKB/IL-6/JAK2/STAT3 axis." (PMID 41044672, 2025). "Mutations in genes like JAK1 and JAK2 may disrupt normal immune responses, contributing to the tumor’s ability to metastasize and resist therapies." (PMID 39925800, 2025). "JAK2 inhibitors inevitably inhibit the normal hematopoietic function of the body, which can cause anemia, thrombocytopenia, and other adverse effects (including dizziness, headache, abdominal pain, diarrhea, and the secondary tumor)." (PMID 38699644, 2024). "Furthermore, we explored the association of JAK2 mutation with the tumor immune microenvironment in a multiomics cohort." (PMID 38200372, 2024). "In addition, regarding the tumor immune microenvironment, our study revealed that JAK2-mutated cancers had abundant immune cells and greater immune activity." (PMID 38200372, 2024).